PGR (progesterone receptor)
Diseases named in the same sentence as PGR in open-access papers (continued):
Sharing a sentence is not in itself a finding about the gene and the disease.
breast cancer (continued). "For example, we reveal that PGR phosphorylation is correlated with sensitivity to endocrine therapy in PGR-positive breast cancer." (PMID 32686665, 2020). "Triple-negative (TN) breast cancer lacks expression of estrogen receptor (ER), progesterone receptor (PR) as well as the expression and/or gene amplification of human epidermal growth factor receptor 2 (HER2)." (PMID 32012648, 2020). "In current clinical practice, the treatment of breast cancer is based not only on the T and N stages of patients but also on the status of estrogen receptor (ER), progesterone receptor, and human epidermal growth factor receptor-2 (HER-2)." (PMID 33238939, 2020). "Estrogen receptor (ER)-positive and/or progesterone receptor (PgR)-positive breast cancer accounts for approximately 70% of all breast cancers, and 85% of those in women over 70 years of age." (PMID 32690069, 2020). "Breast cancer is molecularly classified by the expression of estrogen receptor (ER), progesterone receptor (PR) and human epidermal growth factor receptor-2 (HER-2)." (PMID 32194848, 2020). "In estrogen receptor (ER) +/progesterone receptor (PR) + breast cancer cells, a novel functional connection between PTEN and autophagy is described as a tumor suppressor pathway (point 1)." (PMID 32708484, 2020). "This review will cover principally the development of agents to image the estrogen receptor (ER) and the progesterone receptor (PgR) in breast cancer and the androgen receptor (AR) in prostate cancer." (PMID 32718075, 2020). "Currently, molecular histology is applied to characterize breast cancer subtypes according to the presence of estrogen receptor (ER), progesterone receptor (PR) and human epidermal growth factor II (HER-2)." (PMID 33348924, 2020). "In regard to association with patient outcomes in breast cancer, ERβ expression is an independent prognostic marker in ERα+-progesterone receptor positive breast cancer." (PMID 33194742, 2020). "Breast cancer can be divided clinically by the expression of estrogen receptor (ER), progesterone receptor (PR), and the human epidermal growth factor receptor 2 (HER2)." (PMID 32457830, 2020). "In order to investigate this detected mRNA expression, we compared the ERBB2, ESR1, and PGR mRNA expression in available TCGA breast cancer samples and grouped the expression values by the annotated result of the immunohistochemistry (IHC) assay." (PMID 32793490, 2020). "Breast cancer is classified into three major subtypes based on the expression of the molecular markers such as estrogen receptor (ER), progesterone receptor (PR), and human epidermal growth factor receptor 2 (HER2)." (PMID 32509375, 2020). "Clinically, breast cancer is subdivided into four main molecular subtypes based on the expression of the estrogen receptor (ER), progesterone receptor (PR) and human epidermal growth factor receptor 2 (HER2), as well as the proliferative index (Ki67)." (PMID 31936750, 2020). "Triple-negative breast cancer (TNBC) is the most aggressive subtype of breast cancer that lacks expression of estrogen receptor (ER) and progesterone receptor (PR) and the human epidermal growth factor receptor 2 (HER2) gene." (PMID 32477007, 2020). "Treatment decisions in breast cancer patients are based on tumor predictive markers [estrogen receptor (ER), progesterone receptor (PR), human epidermal growth factor receptor 2 (HER2)], some of which are also prognostic markers (ER, PR, HER2, Ki-67)." (PMID 32852708, 2020). "MR has been reported to crosstalk with the progesterone receptor to induce cell adhesion and growth inhibition in breast cancer cells." (PMID 33148314, 2020). "In case of hormone- or growth factor-dependent breast cancers expressing ER (estrogen receptor), PR (progesterone receptor) and/or epidermal growth factor receptor 2 (HER2) targeted treatment options can significantly increase quality of life and survival." (PMID 32053991, 2020).
breast cancer (continued). "This review examines the application of NET in postmenopausal women with locally advanced ER and/or PgR-positive breast cancer." (PMID 32690069, 2020). "Nowadays, the adjuvant treatment for breast cancer patients chosen depends on immunohistochemical pattern of Estrogen receptor(ER), Progesterone receptor(PR) and HER2 status of primary breast tumor." (PMID 32592349, 2020). "Elevated expression of FOXM1 predicts poor survival in ER+ and progesterone receptor-positive breast cancer and in patients treated with adjuvant chemotherapy or tamoxifen." (PMID 32976773, 2020). "The highest EZH2 protein expression levels were observed in TNBC, while the lowest expression levels were found in estrogen receptor (ER)/progesterone receptor (PR)-positive breast cancers with low proliferative index." (PMID 33050946, 2020). "A study from the USA revealed only 3.1% of women with ER and/or PgR+ breast cancer received NET compared to 24.7% who received NCT." (PMID 32690069, 2020). "In the last few decades, the treatment efficacy of breast cancer has improved tremendously, and various prognostic biomarkers such as estrogen receptor (ER), progesterone receptor (PR), and human epidermal growth factor receptor 2 (HER2) have been identified." (PMID 32902412, 2020). "For patients with locally advanced estrogen receptor or progesterone receptor-positive breast cancer, neoadjuvant endocrine therapy (NET) facilitates down-staging of the tumor and increased rates of breast-conserving surgery." (PMID 32690069, 2020). "Treatment with sirolimus alone lowered expressions of ER and PgR of breast cancer and reduced tumor size." (PMID 33112549, 2020). "Medical and breast cancer disease history were recorded: 73.3% of patients in the SA population had an oestrogen receptor positive tumour and 50.5% of patients a progesterone receptor positive tumour." (PMID 32240454, 2020). "As breast cancer is a highly heterogeneous disease, scientists divide breast cancers into different clinically relevant molecular subtypes based on the expression levels of the estrogen receptor (ER), progesterone receptor (PR), and HER2." (PMID 33225954, 2020). "In vivo and in vitro preclinical studies have demonstrated that PR function can be blocked by prototypical anti-progestogens known as selective progesterone receptor modulators (SPRMs), mifepristone or onapristone to control breast cancer progression." (PMID 32867363, 2020). "We looked at clinical estrogen receptor (ER), progesterone receptor (PR), and Her2 status in breast cancer, which are important predictive and prognostic molecular markers currently assessed by molecular immunohistochemistry (IHC) staining." (PMID 32350370, 2020). "The Luminal A and B breast cancer subtypes express hormone receptors, estrogen receptor (ER) and progesterone receptor (PR)." (PMID 32401758, 2020). "The results will provide useful information about the side effects of different adjuvant endocrine drugs on lipid profiles in postoperative breast cancer patients (estrogen receptor-positive and/or progesterone receptor-positive)." (PMID 31914031, 2020). "In a meta-analysis of patients who underwent neoadjuvant chemotherapy for breast cancer, ER and PgR discordance rates of 2.5–17% and 5.9–51.7%, respectively, were reported." (PMID 32248830, 2020). "Second, breast cancer subtypes are roughly defined by ER, PgR, and HER2 status in the SEER database." (PMID 33072554, 2020). "Other investigators have grouped and classified breast cancers according to the expression of the important functional markers estrogen receptor (ER), progesterone receptor (PR), and HER2, allowing the identification of tumor subtypes with different outcomes." (PMID 32210163, 2020).
breast cancer (continued). "On the other hand, depletion of miR-141-3p increases PgR levels, even in breast cancer cell lines where its expression is ER-dependent." (PMID 32825530, 2020). "Some common diagnostic and prognostic biomarkers such as human epidermal growth factor receptor (HER2), oestrogen receptor (ER) and progesterone receptor (PR) can guide therapy in breast cancer." (PMID 32618411, 2020). "Estrogen receptor and progesterone receptor expression in breast cancer is so far the most useful predictive marker." (PMID 32944466, 2020). "CUEDC2 promotes breast cancer progression and endocrine resistance through the degradation of estrogen receptor-α (ERα) and the progesterone receptor (PR)." (PMID 33099540, 2020). "In the present in-vivo study, all induced mammary tumors in female rats were adenocarcinomas (luminal A subtype) based on the results of the ER and/or PgR positivity and HER2/neu negativity, as in previous report." (PMID 33112549, 2020). "In fact, the value of PgR measurements remains an area of active disagreement in recommendations for best clinical practice in breast cancer." (PMID 32718075, 2020). "Univariate Cox regression analysis showed that the T category, N category, estrogen receptor (ER) status, progesterone receptor (PR) status, and IQGAP3 expression were significantly associated with survival in breast cancer patients." (PMID 33519444, 2020). "In breast cancer, it was shown that the analysis of only four markers (estrogen receptor, progesterone receptor, HER2, and Ki-67) is enough to make a valid therapeutically relevant molecular classification." (PMID 32252315, 2020). "Breast cancer is clinically divided into subtypes based on molecular expression of biomarkers: estrogen receptor (ER), progesterone receptor (PR), and human epidermal growth factor receptor 2 (HER2)." (PMID 33457427, 2020). "On the molecular level, breast cancer is divided into subtypes based on the expression level of estrogen receptor (ER), progesterone receptor (PR), and human epidermal growth factor receptor 2 (HER2)." (PMID 33260564, 2020). "Three hormonal and growth factor receptors are predominantly used for classification of breast cancers: estrogen receptor (ER), progesterone receptor (PR) and the epidermal growth factor receptor HER2." (PMID 33255471, 2020). "The current biomarkers used in the context of breast cancer treatment are highly dependent on the targeting of oestrogen receptor, progesterone receptor, or HER2, resulting in treatment failure and disease recurrence and creating clinical challenges." (PMID 33138797, 2020). "Kang and colleagues evaluated on a case series of 1848 breast cancer (BC) patients operated for a first primary ER positive HER2 negative BC if Ki67 expression is a significant prognostic factor only when PgR expression is low." (PMID 32917222, 2020). "Information about the expression status of hormone receptors such as estrogen receptor (ER), progesterone receptor (PR), and Her-2 is crucial in the management and prognosis of breast cancer." (PMID 32566676, 2020). "Decisions regarding the selection of breast cancer therapies require an accurate determination of the ER, PgR, and HER2 expression status of the tumor, which are usually determined via biopsy to achieve a definitive diagnosis." (PMID 32248830, 2020). "One of the most abundant subtypes of breast cancer is estrogen and progesterone receptor positive cells (ERα/PR+)." (PMID 32448364, 2020). "Breast cancer is a heterogeneous disease often classified into diverse molecular subtypes as defined by protein expression of the Estrogen Receptor (ER), Progesterone Receptor (PR), and/or the Human Epidermal Growth Factor Receptor 2 (HER2)." (PMID 33003540, 2020).
breast cancer (continued). "NMU is administrated intraperitoneally to animals to induce the oncogenesis of the mammary ducts and yields a high incidence of estrogen and/or progesterone receptor (ER/PgR)-positive mammary tumors." (PMID 33112549, 2020). "These cells are classified as luminal A type of breast cancer cells (estrogen receptor and progesterone receptor positive)." (PMID 32616817, 2020). "We used cell lines characterized by important differences in the three main receptors conventionally used for breast cancer subtyping: The estrogen receptor (ER), progesterone receptor (PR), and human epithelial receptor (HER 2)." (PMID 32751976, 2020). "Based on the receptor status, out of 110 Breast cancer cases 45 (40.90%) were positive for Her2/neu, 62 (56.37%) were carrying estrogen receptor and 72 (64.45%) were +ve for progesterone receptor." (PMID 31983176, 2020). "Breast cancer, the most common cancer among women, can be classified into several subtypes according to the expression of estrogen receptor (ER), progesterone receptor (PR), human epidermal growth factor receptor 2 (HER2), and Ki-67." (PMID 32707869, 2020). "Breast cancer can be divided into four subtypes according to the expression levels of certain molecules, including the estrogen receptor (ER), progesterone receptor (PR), and HER2 protein, as well as Ki67, which represents tumor cells proliferation." (PMID 32497022, 2020). "More than 60% of breast cancers are either estrogen receptor (ER) or progesterone receptor (PR) positive." (PMID 32895397, 2020). "Breast cancer is primarily characterized by the expression of estrogen receptor (ER), progesterone receptor (PR), and/or human epidermal growth factor receptor type 2 (HER2)." (PMID 33374917, 2020). "Breast cancer, one of the most common types of cancer, is classified into different subtypes based on the presence of estrogen receptor (ER), progesterone receptor (PR) and growth factor receptor epidermal 2 (HER-2/neu)." (PMID 33194597, 2020). "To study the effect of hyperglycemia on hormone positive breast cancer, we utilized the estrogen receptor (ER+)/progesterone receptor (PR+) MCF7 breast cancer cell line." (PMID 32230859, 2020). "A more recent study has tracked the time course of PgR level increase in human breast cancer T47D xenografts in mice by biodistribution, with levels continuing to rise even after 2-days of estrogen treatment." (PMID 32718075, 2020). "The well-known classification criteria of breast cancer are depending on the status of molecular markers ER (estrogen receptor), PR (progesterone receptor), Ki-67, and Her2 (human epidermal growth factor receptor 2)." (PMID 33490234, 2020). "In Swedish, Norway, Chinese, and Egyptian cohorts of patients, CD163+ macrophages positively correlated with estrogen and progesterone receptor negativity, triple-negative/basal-like breast cancer and inversely correlated with luminal A breast cancer." (PMID 33194645, 2020). "Three major subtypes of breast cancer (estrogen receptor (ER) and progesterone receptor- (PR) positive, human epidermal growth factor receptor 2 (HER2) overexpression, and TNBC) have different clinical characteristics and outcomes." (PMID 33457427, 2020). "There are currently limited clinical guidelines outlining which neoadjuvant endocrine agent to use, or the optimal duration of use, in postmenopausal women with ER and/or PgR+ breast cancer." (PMID 32690069, 2020). "Breast cancer (BC) is the most common malignancy in women and biomarkers including estrogen receptor (ER)s, progesterone receptor (PR), and human epidermal growth factor receptor 2 (HER2), are routinely performed for therapeutic decision-making." (PMID 32393302, 2020). "ER and PgR are intercellular steroid hormone receptors and have been frequently demonstrated in breast carcinoma." (PMID 32944466, 2020).
breast cancer (continued). "Globally, breast cancer (BC) is the leading cancer type in women, and approximately three‐quarters of all BCs are estrogen receptor (ER) and/or progesterone receptor (PR) positive (Provenzano, Ulaner, & Chin, 2018; Waks & Winer, 2019)." (PMID 32043610, 2020). "Our study disclosed that all malignant breast carcinoma of control tumor tissue are both overexpressed of ER and PgR." (PMID 33112549, 2020). "Women that were diagnosed with estrogen receptor/progesterone receptor positive (ER+/PR+) breast cancers (BC) that also expressed high levels of leptin had poorer prognosis than women with low leptin expression." (PMID 31208047, 2019). "Active treatment can be considered as the default in cases of early ER-positive and HER2-negative breast cancer that satisfy conditions of low PgR and high Ki-67." (PMID 31975992, 2019). "Several breast cancer biomarkers have been identified of which the estrogen receptor (ER), progesterone receptor (PR) and human epidermal growth factor receptor 2 (HER2) constitute the main markers." (PMID 31007609, 2019). "All these types of breast cancer were determined by expression of ER (estrogen receptor), PR (progesterone receptor), HER2 (human epidermal growth factor receptor 2) and proliferative markers such as Ki67 and cytokeratin CK5/6." (PMID 31309004, 2019). "The specific receptors that are evaluated in breast cancer in clinical practice are the estrogen receptor (ER), progesterone receptor (PR), and human epidermal growth factor 2-neu (HER2/neu) receptor." (PMID 30755260, 2019). "Univariate Cox regression analysis revealed that estrogen receptor (ER) status, progesterone receptor (PR) status, MLR, and the PNI all had significant associations with survival in patients with stage N1 breast cancer." (PMID 32083015, 2019). "With the advent and increasing uptake of screening programs, the incidence of early stage, hormone receptor positive (HR + )/luminal-like [estrogen receptor positive (ER + ) and/or progesterone receptor positive (PR + )] breast cancer has continued to rise." (PMID 30976105, 2019). "Recently, more attention has been devoted to the classification of primary breast cancer into molecular subtypes using markers like estrogen receptor (ER), progesterone receptor (PR) and human epidermal growth factor receptor (HER)." (PMID 33860286, 2019). "According to the clinical data, PGC-1β expression is strongly correlation with breast cancer lymph node metastasis or progesterone receptor expression, which was consistent with the expression characteristics in the two cell lines." (PMID 31007610, 2019). "Subsequently, the samples are sequentially stained and treated for antibody removal for 4 markers of interest from the breast cancer panel: estrogen receptor (ER), progesterone receptor (PR), epidermal growth factor receptor 2 (Her2) and cytokeratin (CK)." (PMID 30872751, 2019). "It has been shown that nearly 75% of all breast cancers express estrogen-receptors (ER) and/or progesterone-receptors (PgR), whereas up to 30% of breast cancers show HER2 overexpression." (PMID 31470531, 2019). "Approximately 70% of breast cancers are hormone receptor-positive and express estrogen receptor-α (ERα) or/and progesterone receptor." (PMID 30658681, 2019). "In the current diagnosis and treatment of breast cancer, the most specific markers are estrogen receptor (ER), progesterone receptor (PR), and human epidermal growth factor receptor 2 (HER2)." (PMID 30906412, 2019). "Breast cancer is stratified into four distinct clinical subtypes, using three key biomarkers (Her2/Neu gene status, Estrogen and Progesterone receptor status)." (PMID 30846725, 2019). "As we all know, luminal subtype of breast cancer refers to a subtype of breast cancer with either ER (estrogen receptor) or PR (progesterone receptor) positive together with HER-2 (human epidermal growth factor receptor) negative." (PMID 31480430, 2019).